LINC01703 (long independently transcribed non-coding RNA 1703)
Synonyms: lncPARP1
Gene: Long non-coding RNA gene on chromosome 1 (226,083,478 to 226,090,465, forward strand). Ensembl gene ENSG00000225518.
Diseases named in the same sentence as LINC01703 in open-access papers:
LINC01703 is named in the same sentence as 5 diseases in open-access papers, as found by Europe PMC text mining. Sharing a sentence is not in itself a finding about the gene and the disease. The quoted sentences say what the papers report.
lung adenocarcinoma (1 paper, 2022). A carcinoma that arises from the lung and is characterized by the presence of malignant glandular epithelial cells. "Among them, LINC01703 has been reported to be of great significance in the diagnosis of lung adenocarcinoma." (PMID 36248984, 2022).
lung carcinoma (1 paper, 2023). "Our findings indicate that Linc01703, which is notably downregulated in metastatic lung cancer cells, effectively suppresses lung cancer metastasis in vivo." (PMID 38136327, 2023). "In the current study, we investigated the role of Linc01703, a downregulated lncRNA in metastatic lung cancer cells, in promoting exosome secretion and inhibiting LUAD metastasis." (PMID 38136327, 2023). "We also observed a positive correlation between the expression of Linc01703 and extracellular exosome genes in the Cancer Genome Atlas (TCGA) lung cancer datasets." (PMID 38136327, 2023). "Interestingly, Linc01703 does not directly impact the proliferation and invasion capabilities of lung cancer cells but rather inhibits cancer metastasis by promoting the secretion of CD81+ exosomes through the Rab27a/SYTL1/CD81 transport complexes." (PMID 38136327, 2023).
cancer (1 paper, 2023). A tumor composed of atypical neoplastic, often pleomorphic cells that invade other tissues. "Considering the important role of Linc01703-induced CD81+ exosome release, our findings provide new insights into the potential clinical application of CD81+ exosome-related cancer therapy." (PMID 38136327, 2023).
LINC01703 also shares sentences with these, for which no sentence is quoted: hepatocellular carcinoma (1 paper); tumor (1).